MIR548X2 (microRNA 548x-2)
Synonyms: hsa-mir-548x-2
Gene: MicroRNA gene on chromosome 13 (65,966,330 to 65,966,429, reverse strand). Ensembl gene ENSG00000263581.
Gene Ontology:
Biological process: miRNA-mediated post-transcriptional gene silencing
Cellular component: RISC complex
Homologues: Orthologues: chimpanzee MIR548X2 (100% identical). Paralogues in human: MIR548Z (75% identical), MIR548H3 (74% identical), MIR548AZ (71% identical), MIR548AY (69% identical), MIR548AN (68% identical), MIR548AA1 (67% identical), MIR548K (67% identical), MIR548N (62% identical), MIR548F1 (61% identical), MIR548P (61% identical), MIR548AH (60% identical), MIR548AX (60% identical), and 13 more.